FZD1 (frizzled class receptor 1)
Description:
Receptor for Wnt proteins. Activated by WNT3A, WNT3, WNT1 and to a lesser extent WNT2, but apparently not by WNT4, WNT5A, WNT5B, WNT6, WNT7A or WNT7B. Contradictory results showing activation by WNT7B have been described for mouse (By similarity). Functions in the canonical Wnt/beta-catenin signaling pathway. The canonical Wnt/beta-catenin signaling pathway leads to the activation of disheveled proteins, inhibition of GSK-3 kinase, nuclear accumulation of beta-catenin and activation of Wnt target genes. A second signaling pathway involving PKC and calcium fluxes has been seen for some family members, but it is not yet clear if it represents a distinct pathway or if it can be integrated in the canonical pathway, as PKC seems to be required for Wnt-mediated inactivation of GSK-3 kinase. Both pathways seem to involve interactions with G proteins. May be involved in transduction and intercellular transmission of polarity information during tissue morphogenesis and/or in differentiated tissues (Probable). (Microbial infection) Acts as a receptor for C.difficile toxin TcdB in the colonic epithelium.
Synonyms: hFz1; DKFZp564G072
Tractability: Antibody: a drug acting on it is in phase 2 or 3 trials; UniProt places it where antibodies can reach, with high confidence; its Gene Ontology location is reachable by antibodies, with high confidence; UniProt predicts a signal peptide or a membrane-spanning region; the Human Protein Atlas places it where antibodies can reach. PROTAC: UniProt records ubiquitination sites on it; ubiquitination databases record sites on it; a small molecule that binds it is known.
Target class: Frizzled family G protein-coupled receptor; Membrane receptor
Gene: Protein-coding gene on chromosome 7 (91,264,433 to 91,271,326, forward strand). Ensembl gene ENSG00000157240.
Subcellular location: Cell membrane
Subcellular location (Human Protein Atlas): Plasma membrane
Pathways (Reactome):
Signal Transduction: Asymmetric localization of PCP proteins; Class B/2 (Secretin family receptors); Disassembly of the destruction complex and recruitment of AXIN to the membrane; PCP/CE pathway; TCF dependent signaling in response to WNT
Gene Ontology:
Molecular function: frizzled binding; PDZ domain binding; protein binding; signaling receptor binding; Wnt receptor activity; Wnt-protein binding; transmembrane signaling receptor activity
Biological process: autocrine signaling; canonical Wnt signaling pathway; cell-cell signaling; positive regulation of DNA-templated transcription; positive regulation of osteoblast differentiation; positive regulation of transcription by RNA polymerase II; regulation of mesenchymal stem cell differentiation; response to xenobiotic stimulus; midbrain dopaminergic neuron differentiation; neuron differentiation; non-canonical Wnt signaling pathway; positive regulation of neuron projection development; presynapse assembly; astrocyte-dopaminergic neuron signaling; cell surface receptor signaling pathway; negative regulation of oxidative stress-induced neuron intrinsic apoptotic signaling pathway; regulation of presynapse assembly
Cellular component: cell surface; focal adhesion; plasma membrane; Wnt signalosome; membrane
Genetic constraint (gnomAD): Loss-of-function variants: 21 observed, 44.24 expected, observed/expected ratio (o/e) 0.47, 90% interval 0.34 to 0.68. The upper end of that interval is the gene's LOEUF score, 0.68, which puts it in group 2 of 6, group 1 being the genes least tolerant of losing a copy. Missense variants: 793 observed, 853.71 expected, observed/expected ratio (o/e) 0.93, 90% interval 0.88 to 0.99. Synonymous variants: 449 observed, 377.73 expected, observed/expected ratio (o/e) 1.19, 90% interval 1.1 to 1.28.
Homologues: Orthologues: dog FZD1 (97% identical), guinea pig FZD1 (94% identical), mouse Fzd1 (94% identical), rat Fzd1 (94% identical), chimpanzee FZD1 (86% identical), pig FZD1 (85% identical), rabbit FZD1 (78% identical), zebrafish fzd1 (69% identical), Drosophila melanogaster fz3 (23% identical), Caenorhabditis elegans sfrp-1 (9% identical). Paralogues in human: FZD2 (69% identical), FZD7 (69% identical), FZD8 (43% identical), FZD5 (42% identical), FZD10 (40% identical), FZD3 (38% identical), FZD4 (37% identical), FZD9 (37% identical), FZD6 (37% identical), SMO (25% identical), SFRP4 (14% identical), FRZB (14% identical), and 3 more.
Diseases named in the same sentence as FZD1 in open-access papers:
FZD1 is named in the same sentence as 73 diseases in open-access papers, as found by Europe PMC text mining. Sharing a sentence is not in itself a finding about the gene and the disease. The quoted sentences say what the papers report.
breast cancer (18 papers, 2006 to 2025). A primary or metastatic malignant neoplasm involving the breast. "For instance, FOXF2 plays diverting roles on WNT2B and FZD1 promoters in lumenal breast cancer and BLBC." (PMID 40003882, 2025). "SFRPs interact with FZDs, and MBD2 alternative splicing inhibits FZD1 activation under hypoxic conditions, thereby promoting breast cancer metastasis." (PMID 40860197, 2025). "FZD1 (Frizzled Class Receptor 1) has been found to mediate the multi-drug resistance in breast cancer by regulating the WNT/β-catenin signaling pathway." (PMID 37914721, 2023). "The specificity of TcdBFBD for FZD1/2/7 allows us to establish this agent as an effective targeted therapy for FZD1/2/7+ and/or cisplatin-resistant mammary tumor cells." (PMID 37943878, 2023). "Other researchers have demonstrated that targeting FZD1 reverses multidrug resistance in neuroblastomas and breast cancer cells." (PMID 26048374, 2015). "Since JCAD, as an upstream of FZD1, is closely related to breast cancer prognosis and exosomes play a role in tumor resistance, investigating this signaling pathway and its implications for drug resistance in breast cancer is highly important." (PMID 40860197, 2025). "Furthermore, FZD1/2/7–positive cells are enriched in chemotherapy-resistant cells in both basal-like and luminal mammary tumors treated with cisplatin, and TcdBFBD synergizes strongly with cisplatin in inhibiting both tumor types." (PMID 37943878, 2023). "FZD1 appears to mediate drug resistance by modulating the Wnt/β-catenin pathway in clear cell renal cell carcinoma, neuroblastoma, pancreatic ductal adenocarcinoma, ovarian cancer, and breast cancer." (PMID 36755291, 2023). "FZD1/2/7 form a subgroup with nearly identical CRDs within the FZD family and FZD7 has been previously shown to be associated with triple-negative breast cancer and targeting FZD7 may reduce growth of breast cancer cells." (PMID 37943878, 2023). "Overall, these results suggested that JCAD activates the Wnt/β-catenin pathway by promoting an increase in downstream FZD1 expression, which mediates the EMT process and ultimately promotes breast cancer progression." (PMID 40860197, 2025). "In luminal breast cancer cells, FOXF2 initiates the recruitment of NCoA3, forming a complex that attaches to the WNT2B and FZD1 promoters." (PMID 40003882, 2025). "Mechanistically, the present study revealed that JCAD activates the Wnt/β-catenin pathway by increasing downstream FZD1 expression, thereby mediating the EMT process and promoting breast cancer progression." (PMID 40860197, 2025). "As a result, MDB2a transcriptionally activates frizzled class receptor 1 (FZD1) expression and promotes EMT and metastasis in breast cancer cells." (PMID 37583933, 2023). "Comprehensive overview of ligand (WNT1-16) and receptor (FZD1-10, LRP5-6, ROR1-2, RYK, PTK) genes and their implication in human breast cancer based on a survey of the primary literature." (PMID 32083079, 2020). "The Frizzled 1 protein (FZD1), an important member of the Wnt/β-catenin pathway, and P-gp have been shown to increase in the adriamycin resistant MCF-7 breast cancer cell line." (PMID 29805346, 2018). "The Frizzled 1 and 2 receptors (FZD1 and FZD2) are also overexpressed in breast cancer, and high β-catenin activity is significantly correlated with poor prognosis in breast cancer patients." (PMID 16933995, 2006). "Therefore, in luminal breast cancer and basal-like breast cancer cells, FOXF2 differentially modulates the transcription of WNT2B and FZD1 by enlisting NCoA3 and NCoR1, respectively." (PMID 40003882, 2025). "The experimental results demonstrated that JCAD may activate the Wnt/β-catenin pathway by increasing FZD1 expression, thereby promoting the EMT process and breast cancer progression." (PMID 40860197, 2025).
breast cancer (continued). "Here, we developed a fragment of C. difficile toxin B (TcdBFBD), which recognizes and inhibits a subclass of FZDs, FZD1/2/7, and examined whether targeting this FZD subgroup may offer therapeutic benefits for treating breast cancer models in mice." (PMID 37943878, 2023). "FZD1 and Pygopus Family PHD Finger 2 (PYGO2), a recently discovered co-activator of Wnt/β-catenin -dependent transcription, were found overexpressed in chemotherapy-resistant breast cancer cell lines and to be essential for the maintenance of MDR1 expression." (PMID 35663403, 2022). "To confirm differential gene expression levels in the three breast cancer subtypes, Her2+, ER + and TNBC, we selected 6 genes (ITGA3, ITGA5, OXTR, WNT5B, BCAR1, FZD1) with significantly different levels of expression based on our microarray studies and validated their expression levels by qRT-PCR." (PMID 22954256, 2012). "Although the present study did not fully elucidate the mechanisms by which JCAD regulates FZD1 and the exploration of exocrine levels is still in its infancy, the present findings provide a basis for further investigations of JCAD function in breast cancer." (PMID 40860197, 2025).
neuroblastoma (11 papers, 2014 to 2023). Neuroblastoma (NB) is the most common solid, extracranial childhood tumor. "For example, FZD1 is oncogenic in lymphoma and neuroblastoma but in prostate cancer is methylated early in lesion progression, suggesting a suppressive role." (PMID 35924166, 2022). "FZD1 mediates chemoresistance in neuroblastoma through activation of the Wnt/beta-catenin pathway by increasing cell proliferation and survival." (PMID 33968932, 2021). "It has been reported that FZD1 silencing induced parallel strong decrease in the expression of MDR1 (multidrug resistance) gene with a significant restoration of drug sensitivity in neuroblastoma (NB) cancer cells, which confirmed the FZD1-associated chemoresistance." (PMID 29789460, 2018). "Other genes (PTK2, NAV3, NAV1, FZD1 and ATRX), expressed in neuroblastoma and involved in cell invasion and migration were mutated at frequency ranged from 4% to 2%." (PMID 27009842, 2016). "Additional five mutated genes (LRRC17, PXDN, FZD1, ARHGEF10L, ATRX) were highly expressed in neuroblastoma and involved in cancer progression." (PMID 27009842, 2016). "Of particular interest is the gene FZD1 because it promotes chemoresistance in neuroblastoma through activation of the Wnt/beta-catenin pathway." (PMID 27009842, 2016). "The Wnt receptor, Fzd1, was upregulated in a doxorubicin-resistant neuroblastoma cell line, and Fzd1-slienced drug-resistant cells had reduced ABCB1 expression levels and were sensitive to chemotherapeutic treatment." (PMID 25401518, 2014). "Examples include high FZD1 expression associated with chemoresistance, FZD6 marking highly tumorigenic stem-like cells in mouse and human neuroblastoma, and FZD2-dependent proliferation of neuroblastoma lines." (PMID 29505958, 2018). "For example, FZD1 silencing induces a strong decrease of multidrug resistance protein 1 (MDR1) expression to enhance drug resistance in neuroblastoma (NB)." (PMID 33832493, 2021). "Other five genes (LRRC17, PXDN, FZD1, ARHGEF10L, ATRX) resulted to be expressed in neuroblastoma and involved in cell migration and invasion." (PMID 27009842, 2016).
glioma (5 papers, 2017 to 2025). A benign or malignant brain and spinal cord tumor that arises from glial cells (astrocytes, oligodendrocytes, ependymal cells). "A marked increase in the expression of FZD1/2/4/5/6/7/8/10 was positively associated with the progression of gliomas from grade II to grade IV." (PMID 36699699, 2022). "High expression of FZD1, 2, 5, 6, 7, and 8 correlates with oncogenic mTOR signaling and poor prognosis in gliomas." (PMID 40430278, 2025). "Meanwhile, univariate analysis revealed that high expression of FZD1/2/5/6/7/8 was an unfavorable factor in glioma." (PMID 36699699, 2022). "Taken together, these findings suggest that FZD2 and FZD6 may serve as independent predictors of poor prognosis in glioma, and FZD1/5/7/8 may be a disadvantageous factor." (PMID 36699699, 2022). "In summary, our preliminary findings revealed that FZD1/2/5/6/7/8 may be a disadvantageous factor for glioma, whereas FZD2/6 may serve as a novel independent predictor of poor prognosis." (PMID 36699699, 2022). "FZD1/2/5/6/7/8 could be an unfavorable prognostic factor in glioma and FZD2 and FZD6 may be novel independent predictors of poor prognosis in glioma." (PMID 36699699, 2022). "Moreover, our findings confirmed that the high expression of FZD1/2/5/6/7/8 was a disadvantageous factor in glioma, while FZD2 and FZD6 could positively serve as independent predictors of poor prognosis." (PMID 36699699, 2022). "Consistent with our results, high expression of HDAC1, CASP3, REST, GNAI3, FZD1, EPHB4 was found to correlate with poor prognosis of glioma, and inhibitors of HDAC1 inhibited the EMT process in glioma cells thereby affecting cell migration and invasion." (PMID 38629068, 2024).
ovarian carcinoma (5 papers, 2015 to 2023). A malignant neoplasm originating from the surface ovarian epithelium. "For instance, it was shown that the majority of epithelial ovarian cancer tumors exhibited positive staining for FZD1, and it was associated with chemo-resistance via the Wnt/Beta-catenin pathway." (PMID 26100469, 2015). "Since aberrant activation of the canonical Wnt pathway plays a critical role in OC development, and in epithelial ovarian cancer FZD1 expression is increased, we examined Wnt pathway gene expression following F7 and/or niraparib treatments of the two examined cell lines (HTB75 and HTB161)." (PMID 36364346, 2022). "In OC, for example, FZD1 expression was increased in epithelial ovarian cancer." (PMID 36364346, 2022). "Encouragingly, ROSI exerts reversing effects in chemo-resistant ovarian cancer and melanoma cells via suppression of Frizzled-1 (FZD1), which enhances the inhibition of Wnt/β-catenin pathway, and the subsequent decreased expression of MDR1/P-gp, which is a common cause of MDR." (PMID 34631571, 2021).
colorectal cancer (4 papers, 2014 to 2025). A primary or metastatic malignant neoplasm that affects the colon or rectum. "The KEGG pathways “colorectal cancer” and “pathways in cancer” were enriched in the downregulated PM cluster and included Frizzled receptors FZD1, 2, 4, 6, and 7 and signaling protein WNT5a, all key members of the wnt pathway." (PMID 24906157, 2014).
pancreatic cancer (4 papers, 2014 to 2025). "For instance, Vantictumab (OMP-18R5), a monoclonal neutralizing antibody against FZD1/2/5/7/8, has been evaluated in clinical trials for breast and pancreatic cancers." (PMID 41286306, 2025). "Overexpression of Frizzled receptors (FZD1, 2, 7, 9) and their ligands (WNT2, 3, 4, 5A, 5B, etc.)was detected in pancreatic cancer patients compared to those with a normal pancreas." (PMID 32707920, 2020).
clear cell renal cell carcinoma (3 papers, 2020 to 2023). "FZD1, upregulated in sunitinib-resistant clear cell renal cell carcinoma cells, was associated with the resistance of sunitinib." (PMID 34781823, 2021). "However, alterations in FZD1 in renal clear cell carcinoma were associated with better OS and DFS." (PMID 32432037, 2020).
colon cancer (3 papers, 2013 to 2023). "Previous research found that the gradient effect of FZD1 expression in the tumor microenvironment may regulate colon cancer progression and spread, providing a new therapeutic target for colon cancer patients." (PMID 36755291, 2023).
gastric cancer (3 papers, 2021 to 2024). A primary or metastatic malignant neoplasm involving the stomach. "Fzd1 has also been observed to play a role in tumorigenesis in breast cancer, gastric cancer, and non-small cell lung cancer (NSCLC)." (PMID 34671643, 2021). "For example, miR-135a and miR-8052 act as tumor suppressors in gastric cancer by inhibiting Fzd1 expression, EMT, and cell migration." (PMID 34671643, 2021). "VIM antisense RNA 1 (VIM-AS1) expression enhanced tumorigenic pathways by downregulating miR-8052 expression and increasing expression of Fzd1 in human gastric cancer (GC) tissue." (PMID 34671643, 2021). "FZD1 and FZD8 as oncogenes promote the proliferation, invasion, and migration of gastric cancer cells, and high expression of FZD8 suggests that a patients has a poor prognosis." (PMID 38952556, 2024).
lung carcinoma (3 papers, 2021 to 2022). "For example, in patients with lung cancer, higher FZD2 expression was associated with improved survival; also, in patients with high-grade serous carcinoma after chemotherapy, the high level of FZD1 was associated with longer OS." (PMID 35178201, 2022).
non-small cell lung carcinoma (3 papers, 2018 to 2020). A group of at least three distinct histological types of lung cancer, including non-small cell squamous cell carcinoma, adenocarcinoma, and large cell carcinoma. "A recent study has shown that downregulation of FZD1 by miR-135b reversed chemoresistance of non-small cell lung cancer (NSCLC) cells, further confirmed the association between FZD1 and chemoresistance." (PMID 29789460, 2018). "OMP-18R5 (Vantictumab) targets the FZD1, FZD2, FZD5, FZD7, and FZD8 frizzled protein receptors to block WNT signaling are being investigated in phase I clinical trials in breast, pancreatic, and non-small cell lung cancer." (PMID 32758244, 2020).
prostate carcinoma (3 papers, 2009 to 2022). A carcinoma that arises from epithelial cells of the prostate gland. "Genetic aberrations in the seven-transmembrane family of Frizzled Wnt receptors (FZD1-10) are reported in a number of human solid cancers, including prostate cancer." (PMID 35204808, 2022). "The frequency of FZD1/2/3/4/5/7/8/10 gene amplification in primary prostate cancer is also relatively low (≤3%), with incidence increasing slightly in metastatic disease (≤4.5%)." (PMID 35204808, 2022).